EEIG2 (EEIG family member 2)
Synonyms: FAM102B; DKFZp779B126; SYM-3B
Tractability: PROTAC: ubiquitination databases record sites on it.
Gene: Protein-coding gene on chromosome 1 (108,560,036 to 108,644,900, forward strand). Ensembl gene ENSG00000162636.
Subcellular location (Human Protein Atlas): Cytosol; Nucleoli
Genetic constraint (gnomAD): Loss-of-function variants: 11 observed, 32.86 expected, observed/expected ratio (o/e) 0.33, 90% interval 0.21 to 0.55. The upper end of that interval is the gene's LOEUF score, 0.55, which puts it in group 2 of 6, group 1 being the genes least tolerant of losing a copy. Missense variants: 294 observed, 371.33 expected, observed/expected ratio (o/e) 0.79, 90% interval 0.72 to 0.87. Synonymous variants: 109 observed, 134.11 expected, observed/expected ratio (o/e) 0.81, 90% interval 0.69 to 0.95.
Homologues: Orthologues: chimpanzee EEIG2 (100% identical), macaque EEIG2 (99% identical), guinea pig EEIG2 (96% identical), pig EEIG2 (96% identical), mouse Eeig2 (95% identical), rat Eeig2 (94% identical), dog EEIG2 (87% identical), rabbit EEIG2 (86% identical), tropical clawed frog eeig2 (81% identical), zebrafish fam102bb (78% identical), zebrafish eeig2a (68% identical). Paralogues in human: EEIG1 (62% identical).
Diseases named in the same sentence as EEIG2 in open-access papers:
EEIG2 is named in the same sentence as 4 diseases in open-access papers, as found by Europe PMC text mining. Sharing a sentence is not in itself a finding about the gene and the disease.
EEIG2 shares sentences with these, for which no sentence is quoted: hyperglycaemia (1 paper); Insulin resistance (1); type 1 diabetes (1); type 2 diabetes (1).